HP (haptoglobin)
Diseases named in the same sentence as HP in open-access papers (continued):
Sharing a sentence is not in itself a finding about the gene and the disease.
liver disease (19 papers, 2012 to 2025). "The findings advocate for the screening of serum ferritin (and perhaps haptoglobin) in T2DM patients with MASLD to identify those at higher risk of liver disease progression." (PMID 41010909, 2025). "Furthermore, the diagnostic workup has to consider some specific aspects of liver disease, which include, for instance, the impact of liver dysfunction on circulating haptoglobin levels." (PMID 33499290, 2021). "Clinically, Apo-A1 is routinely combined with alpha-2-macroglobulin (A2M) and haptoglobin (HP) to facilitate monitoring of the progression of the liver disease." (PMID 40809427, 2025). "Haptoglobin, an acute-phase protein that scavenges cell-free hemoglobin, has also been studied as a biomarker of liver disease severity." (PMID 39521382, 2024). "It is decreased or undetectable in hemolysis of any kind, but low haptoglobin levels are observed in liver disease because its production is impaired." (PMID 33499290, 2021). "In liver disease, studies were focused on the pattern of glycosylation of serum proteins: An increase in fucosylation and branching of haptoglobin was observed in alcoholic liver disease." (PMID 34064584, 2021). "Somewhat older data exists on fucosylation of haptoglobin in liver disease and shows hyperfucosylation in patients with alcoholic liver disease and primary biliary cholangitis." (PMID 32557671, 2020). "The concentration of serum haptoglobin can be low in the presence of liver disease, hemolytic anemia, ineffective erythropoiesis in myelodysplastic syndrome, hereditary ahaptoglobinemia, and with pregnancy and estrogen therapy." (PMID 28203576, 2017). "HP is a positive acute phase protein and has long been used for the study of various liver diseases such as viral hepatitis and HCC." (PMID 24066001, 2013). "There is also evidence to suggest that glycoforms of haptoglobin may be useful in differentiating various stages and etiologies of liver disease." (PMID 39521382, 2024). "ApoA1 and haptoglobin have been applied in the current test system for liver disease." (PMID 29179490, 2017). "A comprehensive assessment of the haptoglobin glycosylation status from differing liver disease conditions might be valuable for identifying predictive liver disease markers in future studies." (PMID 27725718, 2016). "Not only the amount but also different isoforms of HP may change in liver diseases; therefore, it has long been used for studying various liver diseases including liver cancer." (PMID 24497876, 2014). "Finally, in these severe liver diseases, haptoglobin should also be significantly decreased, which was not the case." (PMID 33216772, 2020).
pancreatic cancer (19 papers, 2007 to 2022). "Other common serum markers of inflammation such as haptoglobin, leukocytes and albumin, are less well studied in relation to the risk of pancreatic cancer even though they have been found to be associated with other malignancies." (PMID 31464604, 2019). "We found an increased risk of pancreatic cancer associated with pre-diagnostic serum levels of haptoglobin, CRP and leukocytes." (PMID 31464604, 2019). "We found an increased risk of developing pancreatic cancer when participants have increased levels of haptoglobin, CRP and leukocytes, serum markers of inflammation." (PMID 31464604, 2019). "A detection kit for pancreatic cancer via a sandwich enzyme-linked immune sorbent assay using Aleuria aurantia lectin and the Fab portion of anti-haptoglobin antibody has been reported." (PMID 24576319, 2014). "The current study aimed to evaluate associations between standard pre-diagnostic serum markers of chronic inflammation (CRP, albumin, haptoglobin and leukocytes) and pancreatic cancer risk in the prospective Swedish Apolipoprotein-related MORtality RISk (AMORIS) cohort study." (PMID 31464604, 2019). "In this study, we evaluated associations between standard pre-diagnostic serum markers of chronic inflammation (CRP, albumin, haptoglobin and leukocytes) and pancreatic cancer risk in the Swedish Apolipoprotein-related MORtality RISk (AMORIS) prospective cohort study." (PMID 31464604, 2019). "We previously reported that serum from patients with pancreatic cancer shows an increase in fucosylated proteins with a molecular weight of 40 kD, which we identified as haptoglobin (Hp) beta chains." (PMID 36313594, 2022). "In this study, by interrogating serum data from 61,597 healthy subjects in the AMORIS cohort with follow-up of 18 years, we found evidence for a positive association between serum haptoglobin, CRP and leukocytes, and the risk of developing pancreatic cancer." (PMID 31464604, 2019). "We observed a positive association between haptoglobin, CRP and leukocytes and the risk of pancreatic cancer." (PMID 31464604, 2019). "We previously reported increased levels of fucosylated haptoglobin (Fuc-Hpt) in the sera of patients with pancreatic cancer, based on lectin blot analysis using Aleuria aurantia lectin (AAL), which recognizes all types of fucosylation." (PMID 29560105, 2018). "We previously found that the serum level of fucosylated haptoglobin (Fuc-Hpt) was significantly increased in pancreatic cancer patients." (PMID 29560105, 2018). "An increase in Lewis- and core-type fucosylation of haptoglobin has been reported in patients with pancreatic cancer (PC), suggesting that fucosylated haptoglobin is a candidate PC biomarker." (PMID 28455724, 2017). "Highly fucosylated haptoglobin (Fuc-Hpt) was identified as a potential biomarker in pancreatic cancer upon Aleuria aurantia lectin (AAL) blot analysis of the serum of pancreatic cancer patients." (PMID 26509158, 2015). "Positive rates of fucosylated haptoglobin with this method were significantly higher in patients of stage IV pancreatic cancer, compared with other clinical stages." (PMID 24576319, 2014). "Increased levels of fucosylation have been reported in cancer, such as increased core-fucosylation of AFP in HCC, and increased fucosylation of haptoglobin in ovarian, lung, breast and pancreatic cancer." (PMID 20704698, 2010). "They provided preliminary evidence of altered glycosylation of several serum proteins (e.g., α-1-antitrypsin, haptoglobin, α-1-acid glycoprotein 1) prior to pancreatic cancer diagnosis, but stated that further investigation of these proteins as early biomarkers is indicated." (PMID 33800786, 2021). "A combination of α-1-antichymotrypsin (AACT), thrombospondin-1 (THBS1), and haptoglobin (HPT) outperformed CA 19−9 in distinguishing pancreatic cancer from normal controls (AUC = 0.95), patients with diabetes (AUC = 0.89), pancreatic cysts (AUC = 0.82), and chronic pancreatitis (AUC = 0.90)." (PMID 33800786, 2021).
pancreatic cancer (continued). "Where is fucosylated haptoglobin produced in patients with pancreatic cancer?" (PMID 24970126, 2012). "Up-regulation of glycosylation in haptoglobin has been reported in pancreatic cancer." (PMID 22856521, 2012). "Furthermore, in pancreatic cancer patients, site-specific fucosylation of bi-antennary glycans in two sites (N207 and N241) increased, while tri-antennary glycans (glycans containing three branches) increased in four haptoglobin N-glycan sites." (PMID 33466384, 2021). "Glycopeptide, NLFLNHSENATAK from haptoglobin has been reported to have de-sialylated, mono-sialylated and completely sialylated glycan structures, while, only the completely sialylated structure has been shown to be up-regulated in pancreatic cancer samples compared to the controls." (PMID 22856521, 2012). "A pancreatic cancer cell, PSN-1, expresses haptoglobin mRNA and produces fucosylated haptoglobin in conditioned medium." (PMID 24970126, 2012). "Among them, positive (i.e., serum amyloid A, ceruloplasmin, complement factors, haptoglobin) and negative acute-phase reactants (i.e., transthyretin, transferrin) were differentially expressed in sera from ovary, lung, liver, and pancreatic cancer patients." (PMID 23401773, 2013).
Insulin resistance (18 papers, 2009 to 2026). Increased resistance towards insulin, that is, diminished effectiveness of insulin in reducing blood glucose levels. "Retinol-binding protein 4 and haptoglobin protein were downregulated, which are associated with insulin resistance and inflammation, respectively." (PMID 36364802, 2022). "The inflammatory mediators (hs-CRP, Ferritin, Haptoglobin and Adiponectin) exhibited variegated characteristics with the wild typeand heterozygous variant of PPARγ2, thus pointing to the nexus among insulin resistance, inflammation, and adipocyte differentiation." (PMID 37928491, 2023). "This adipose marker could exacerbate insulin resistance as it has been reported than impairment of glucose homeostasis is diminished by haptoglobin deficiency." (PMID 23056516, 2012). "Increased liver iron can promote oxidative stress and insulin resistance; however, these processes may be modulated by haptoglobin polymorphism, and Hp2-2 phenotype would be a risk factor for metabolic syndrome and non-alcoholic fatty liver disease." (PMID 21190397, 2011). "In summary, HG dietary treatment promoted an obese-like metabolic profile that increased insulin resistance and circulating haptoglobin, and resulted in a subtle decrease in semen quality." (PMID 41525320, 2026). "When comparing serum from patients with T2D or insulin resistance to controls' serum, haptoglobin was elevated." (PMID 20927192, 2010). "Interestingly, proteins related to insulin resistance and inflammation-induced hyperglycemia (retinol-binding protein 4 and haptoglobin, respectively) were downregulated after treatment." (PMID 36364802, 2022). "There were positive associations between the platelet count and PTC with white blood cell counts, haptoglobin, and PIIINP, as well as negative associations with red blood cell indices, sex, insulin resistance, and liver markers." (PMID 39768970, 2024). "Age, sex, insulin resistance, systemic hypertension, TG, ALT, AST, GGT, AST/ALT ratio, α2-macroglobulin, haptoglobin, apolipoprotein A1, total bilirubin, fasting blood glucose and fibrosis-4 were found to be associated with NASH and have been used in various diagnostic panels." (PMID 27248665, 2016).
myocardial infarction (17 papers, 2009 to 2025). Gross necrosis of the myocardium, as a result of interruption of the blood supply to the area, as in coronary thrombosis. "These analyses confirmed that HP is significantly overexpressed in myocardial infarction (MI) samples and shows excellent diagnostic efficacy in proteomic data (AUC=0.833)." (PMID 41229424, 2025). "In conclusion, this study establishes Haptoglobin (HP) as a clinically promising diagnostic biomarker and therapeutic target for myocardial infarction through integrated multi-omics analysis and experimental validation." (PMID 41229424, 2025). "The study found that Haptoglobin (HP) is a key gene significantly upregulated in myocardial infarction, and it exhibits high diagnostic value (AUC=0.833) in the proteomic dataset (GSE95368)." (PMID 41229424, 2025). "For example, elevated haptoglobin is associated with increased risk for acute myocardial infarction, stroke, and heart failure." (PMID 28966798, 2017). "Since haptoglobin is as an age-related systemic factor and a significant risk factor for acute myocardial infarction, stroke, and heart failure, we investigated its possible role in functional recovery in our ischemic stroke model." (PMID 28966798, 2017). "In humans the functional allelic polymorphism in the HP gene plays a key role in determining survival and presence of congestive heart failure after myocardial infarction." (PMID 24952741, 2014). "We have recently demonstrated in man that a functional allelic polymorphism in the Haptoglobin (Hp) gene plays a major role in determining survival and congestive heart failure after myocardial infarction (MI)." (PMID 19490627, 2009). "The HP gene is a potential diagnostic biomarker for myocardial infarction, and its specific high expression in classical monocytes implies a potential role in the pathological process of myocardial infarction by regulating the immune microenvironment." (PMID 41229424, 2025). "Moreover, the haptoglobin genotype 2-2 was found to confer a 2-fold increased risk of cardiovascular events (myocardial infarction, stroke and death), when compared to genotypes 1-1 and 2-1 in a recent meta analysis." (PMID 23742649, 2013). "In the context of myocardial infarction (MI), excessive iron deposition and lipid peroxidation cause death of myocardial cells, and upregulation of HP in classical monocytes may represent a compensatory response to alleviate the damage associated with ferroptosis." (PMID 41229424, 2025). "To validate the potential value of the HP gene in myocardial infarction (MI), we conducted validation analysis on two datasets, GSE141512 and GSE95368." (PMID 41229424, 2025). "The expression of HP in peripheral blood of myocardial infarction patients was significantly upregulated (p<0.05)." (PMID 41229424, 2025). "Elevated serum levels of haptoglobin are often observed in response to stress conditions, such as myocardial infarction, tumor, inflammation, trauma and infection, and after the application of certain hormones, including corticosteroids and androgens." (PMID 38655066, 2024). "For examples, haptoglobin level in the plasma was a good prognostic biomarker for acute myocardial infarction." (PMID 28771541, 2017). "In contrast, the investigation of the clots from treatment of heart attack patients showed haptoglobin as main component and only little C3a (data not shown)." (PMID 33584662, 2020).
colorectal cancer (16 papers, 1974 to 2023). A primary or metastatic malignant neoplasm that affects the colon or rectum. "The change in the level of acute-phase reactants, such as CRP, ferritin, fibrinogen, D-dimer, haptoglobin, and albumin, was found to be associated with a dismal prognosis and survival outcome in colorectal cancer patients in various settings of the disease." (PMID 29949857, 2018). "Their results showed that the levels fucosylated haptoglobin were significantly associated with overall and relapse-free survival, distant metastasis, clinical stage, and curability of patients with colorectal cancer." (PMID 28894650, 2017). "High level of haptoglobin has been implicated in patients with colorectal cancer and development of hepatic metastases and it has been stated to be a sensitive indicator." (PMID 22457771, 2012). "This leads to the suggestion of fucosylated haptoglobin as a prognostic marker in addition to CEA for colorectal cancer." (PMID 28894650, 2017). "HP and PDIA3 levels were used as test variables and colorectal cancer was adopted as the state variable (1 = colorectal cancer (including early stage and progressive stage), and 0 = colorectal polyp and group of healthy volunteers) to plot an ROC curve." (PMID 35860021, 2022). "Further stratification analysis revealed that HP and PDIA3 contents were of great assessment value to pathological staging of colorectal cancer, particularly to the progressive stage." (PMID 35860021, 2022). "The plotted ROC curve revealed that the cut-offs of HP and PDIA3 levels indicating colorectal cancer were 149 ug/ml and 66 ng/ml respectively." (PMID 35860021, 2022). "Receiver operating characteristic (ROC) curve demonstrated that the cut-offs of HP and PDIA3 serum contents indicating colorectal cancer were 149 ug/ml and 66 ng/ml respectively." (PMID 35860021, 2022). "Serum levels of HP and PDIA3 were used as test variables and colorectal cancer was adopted as state variable (1 = colorectal cancer, and 0 = colorectal polyp and group of healthy volunteers)." (PMID 35860021, 2022). "The relationships between clinical characteristics and pathological characteristics and the HP and PDIA3 serum contents of colorectal cancer patients at different pathological stages were subsequently analyzed." (PMID 35860021, 2022). "In the screening setting, a multi-marker panel containing HP, LRG1 and PON3 had an AUC of 0.65 for detection of advanced adenomas and another panel, optimized for detecting colorectal cancer, reached an AUC of 0.79." (PMID 34503217, 2021). "There were also significant differences in HP and PDIA3 levels between colorectal cancer patients at an early stage and those at the progressive stage, indicating that HP and PDIA3 expressions were high in malignant tumors and would continuously increase alongside disease progression." (PMID 35860021, 2022). "Value of HP and PDIA3 levels to assessment of colorectal cancer patients." (PMID 35860021, 2022). "Value of HP and PDIA3 levels to assessment of patients with early colorectal cancer." (PMID 35860021, 2022). "Value of HP and PDIA3 levels to assessment of colorectal cancer patients at progressive stage." (PMID 35860021, 2022). "For example, a 5-fold induction of HP indicated the advanced stage in colorectal cancer (50% of the patients at stage CD while none at stage AB)." (PMID 28771541, 2017). "These included up-regulated expression of haptoglobin and lowered expression of antithrombin-III, clusterin, inter-alpha-trypsin inhibitor heavy chain H4, beta-2-glycoprotein I and coagulation factor XIII B chain in the colorectal cancer patients relative to healthy donors." (PMID 28894650, 2017). "Notably, compared to hIgG, hP-sel-Fc had no detectable effects on bleeding times in athymic nude mice xenografted with the tissue specimens of human colorectal cancers." (PMID 25762641, 2015).